MIF (macrophage migration inhibitory factor)
Diseases named in the same sentence as MIF in open-access papers (continued):
Sharing a sentence is not in itself a finding about the gene and the disease.
Obesity (continued). "Mechanistic studies in experimental models of disease have shown that MIF contributes to insulin function in non-pathological glucose homeostasis (i.e., in absence of obesity or disease) but its role is less clear when metabolic stress and pathological processes come into play." (PMID 26124760, 2015). "Nevertheless, given the body of evidence presented, we speculate that small molecule MIF inhibitors may have therapeutic potential to ameliorate obesity-induced IR, halting the progression to T2D and non-alcoholic fatty liver disease." (PMID 25412423, 2014). "Furthermore, treatment of 3T3-L1 adipocytes with TNF-α induced MIF secretion, suggesting that TNF-α may regulate MIF production during obesity." (PMID 23675368, 2013). "It has since emerged that lack of MIF signaling results in an age-dependent impairment of glucose homeostasis in mice fed a chow diet, highlighting the intricacy of this molecule and lack of true clarity in terms of its functional role in obesity-induced IR." (PMID 23675368, 2013). "An MIF-dependent influence on adhesion molecule expression and of macrophage tissue infiltration has been reported in the context of cardiovascular disease (in absence of obesity)." (PMID 20169173, 2010). "In addition, the high plasma MIF levels did not alter adipogenesis gene PPARγ and FASN expression, suggesting that MIF-mediated AMPK/JNK activation in adipose tissue selectively impacted HSL and lipolysis during the development of adipocyte hypertrophy and obesity." (PMID 37935315, 2024). "Our study demonstrated that the tautomerase activity-lacking of MIF significantly alleviated HFD-induced obesity in mice, in which the alleviation may be related to the inhibition of the HFD-induced inflammation and insulin resistance in adipose tissues by the lack of MIF tautomerase activity." (PMID 32265835, 2020).
colorectal cancer (61 papers, 2009 to 2026). A primary or metastatic malignant neoplasm that affects the colon or rectum. "Colorectal cancer (CRC) patients also present elevated MIF levels, which are associated with a worse prognosis." (PMID 33542244, 2021). "Increased MIF has been demonstrated to be associated with poor survival in colorectal cancer, oral squamous cell carcinoma, gastric cancer, and NPC." (PMID 34407796, 2021). "Here, we show that MIF stabilization is tumor-specific in an acute colitis-associated colorectal cancer (CRC) mouse model, leading to tumor-specific functions and selective therapeutic vulnerabilities." (PMID 33542244, 2021). "MIF-deficient mice developed twice as many tumors as WT mice; thus, MIF is involved in the control of colorectal cancer development." (PMID 31360118, 2019). "Another study found that elevated MIF expression in colorectal cancer was associated with an excellent AUC value of 0.933, suggesting that it may be a useful diagnostic marker." (PMID 41159021, 2025). "Furthermore, it has been suggested that MIF has the potential to serve as a diagnostic sign for colorectal cancer." (PMID 38238845, 2024). "MIF (-173 GC/CC) polymorphism, for example, has been demonstrated to be associated with tumor dedifferentiation, advanced illness and poor survival, suggesting that it may be a useful prognostic biomarker for colorectal cancer." (PMID 41159021, 2025). "In addition, the clinical study in colorectal cancer patients found that the serum level of MIF was significantly increased in cancer patients, suggesting that MIF could be used as a diagnostic marker in colorectal cancers." (PMID 19602232, 2009). "tRF-3022b binds to the effects of lectin 1 (LGALS1) and macrophage migration inhibitor (MIF) in colorectal cancer cells, and by regulating MIF in M2 macrophages." (PMID 40726981, 2025). "MIF has been identified as a target of miR-451 in both nasopharyngeal carcinoma and human colorectal cancer cell lines." (PMID 40880391, 2025). "During the process of liver metastasis in colorectal cancer, the interaction between MIF and its receptors, CD74 and CXCR4, is markedly intensified, promoting tumor cell invasion and migration." (PMID 41127012, 2025). "We meticulously analyzed the intricate regulatory network inside the TME of colorectal cancer, namely the immune signaling interactions between tumor cells and macrophages via the MIF-(CD74+CD44) signaling pathway." (PMID 40842994, 2025). "As a consequence, combination treatment was revealed to have a synergistic growth inhibitory impact against refametinib-resistant colorectal cancer cells via inhibiting MIF activation." (PMID 41159021, 2025). "Another study showed that MIF increased oxaliplatin resistance in colorectal cancer by upregulating CXCR7 chemokine." (PMID 41159021, 2025). "Previous studies have reported the interaction of fibroblasts and myeloid cells in colorectal cancer activated protumorigenic signaling pathways such as MIF/CD74 and promoted the aggressive phenotypes." (PMID 38880903, 2024). "Utilizing NUhighepi/NUlowepi as a receptor, the ensuing signaling pathways were found to be closely related to MIF, thereby intimating that nucleotide metabolism and MIF are interwoven and consistently contribute to the exacerbation of colorectal cancer." (PMID 39075485, 2024). "In colorectal cancer, it was shown that MIF promoted macrophage recruitment and angiogenesis to accelerate tumor progression." (PMID 36496973, 2022). "In conclusion, our study revealed that MIF participates in the phenotypic regulation of colorectal cancer cells by targeting SLC3A2." (PMID 35567291, 2022). "In this study, we found that knockdown of MIF suppressed the proliferation, migration and invasion of colorectal cancer cells, and inhibited the progression colorectal cancer in vivo." (PMID 35567291, 2022).
colorectal cancer (continued). "Induction of miR-451 in colorectal cancer cells was able to obstruct Wnt activation by suppressing the translation of its upstream activators, macrophage migration inhibitory factor (MIF) and COX-2." (PMID 32932969, 2020). "Macrophage Migration Inhibitory Factor (MIF) has been identified as a molecular determinant of the anti-EGFR cetuximab resistance in human colorectal cancer cells." (PMID 32245422, 2020). "This is the first paper, to our knowledge, that describes a murine model completely free of MIF protein since the onset of the disease and throughout the development of colorectal cancer." (PMID 31360118, 2019). "Other in vitro and murine colorectal cancer models have shown that MIF promotes tumorigenesis, angiogenesis, migration, and mesenchymal-epithelial transition." (PMID 31360118, 2019). "Increased expression of MIF has been reported in hepatocellular carcinoma, prostate carcinoma, lung adenocarcinoma, neuroblastoma and colorectal cancers." (PMID 23522304, 2013). "Interestingly, similar findings have been reported in colorectal cancer (CRC), where the MIF/CD74 pathway has been implicated in regulating disease progression." (PMID 41562071, 2025). "In colorectal cancer, MIF promotes the migration and invasion of tumor cells by activating the CXCR4 signaling pathway, thereby increasing the risk of tumor metastasis.We further identified the pathways involving core genes and the interaction relationships between the cells." (PMID 40110199, 2025). "Similarly, MIF expression predicts poor survival and increased metastatic potential in colorectal cancer." (PMID 41159021, 2025). "Similarly, in another research, it was found that MIF increases proliferation and inhibits apoptosis of colorectal cancer cells." (PMID 41159021, 2025). "Furthermore, miR-451a functions as a tumour suppressor in papillary thyroid carcinoma and colorectal cancer by targeting the macrophage migration inhibitory factor (MIF), helping to repress cell proliferation and invasion." (PMID 39457889, 2024). "Likewise, our study found that inhibition of MIF suppressed colorectal cancer progression by inhibiting the AKT/GSK‐3β pathway." (PMID 35567291, 2022). "Additionally, our in vivo results verified that MIF regulates the biological behaviour of colorectal cancer cells by targeting SLC3A2 and regulating the AKT/GSK‐3β signalling pathway." (PMID 35567291, 2022). "We found that, despite MIF promoting protumorigenic processes, it may also have a beneficial role at some point during colorectal cancer development." (PMID 31360118, 2019). "To determine the mechanism by which MIF may control colorectal cancer development, we analyzed the T cell and macrophage populations." (PMID 31360118, 2019). "Recently, MIF has been proposed as a possible therapeutic target for colorectal cancer." (PMID 31360118, 2019). "In addition, we identified Macrophage Migration Inhibitory Factor (MIF) as a molecular determinant of the anti-EGFR cetuximab resistance in human colorectal cancer cells." (PMID 31557914, 2019). "Furthermore, significant evidence is emerging linking MIF overexpression with increased invasion and metastasis of colorectal carcinoma supporting a correlation of expression levels of this cytokine with a more aggressive phenotype." (PMID 31557914, 2019). "Similarly, macrophage migration inhibitory factor (MIF) derived from human hepatic sinusoidal endothelial cells (HHSECs) instead of colorectal cancer (CRC) cells, induced migration and EMT and promoted proliferation and apoptotic resistance in CRC cells." (PMID 29197379, 2017). "There were over 40% tumor cells decreased with deletion of endogenous MIF in colorectal carcinoma." (PMID 28915610, 2017). "Similar results were demonstrated in mice grafted with colorectal carcinoma transplants, administered with anti-MIF therapeutics, using either MIF-antibodies or the MIF antagonist (S, R)-3-(4-hydroxyphenyl)-4,5-dihydro-5-isoxazole acetic acid methyl ester (ISO-1)." (PMID 26530123, 2015).
colorectal cancer (continued). "From the literature we know that CEA is increased in tumor tissue, that the MIF (Hs.407995) is up-regulated in colorectal carcinomas, that OPN is significantly higher in CRC tumor tissue compared to normal tissue and that TFRC is higher in tumor tissue compared to normal mucosa." (PMID 24107468, 2013). "MIF has been widely described in colorectal carcinoma (CRC), where elevated serum MIF levels correlate with increased hepatic metastasis and intratumoral macrophage infiltration." (PMID 38732068, 2024). "Hence, MIF has been proposed as a possible therapeutic target for colorectal cancer." (PMID 31360118, 2019). "Here, we use a murine model of chemically induced colitis-associated colorectal cancer wherein tumors develop from the mouse's cells (not by implantation of transformed cells), to determine the influence of MIF in the beginning, as well as in the development of the tumors." (PMID 31360118, 2019). "In colorectal cancer, tRF-3022b, an exosomal tRF, binds to galectin-1 (LGALS1) and macrophage migration inhibitory factor (MIF), modulating MIF levels to reduce M2 macrophage polarization, which impacts tumor growth." (PMID 41376858, 2026). "In research on colorectal cancer, bufalin was shown to target SRC-3 directly, resulting in reduced MIF expression and influencing the polarization of M2 macrophages." (PMID 39123466, 2024). "MIF/CXCR4 signaling promotes neovascularization, migration, and invasion phenotypes in colorectal cancer, non-small cell lung cancer, and glioblastoma." (PMID 35715791, 2022). "Results showed that the levels of MIF and SLC3A2 expression were up‐regulated in colorectal cancer cells." (PMID 35567291, 2022). "We found that the levels of MIF and SLC3A2 mRNA and protein expression were notably increased in the colorectal cancer cells (SW480, SW620, HCT116, HT‐29 and LoVo) when compared with normal epithelial cells (NCM460, FHC)." (PMID 35567291, 2022). "We will continue to explore the roles and mechanisms of MIF and SLC3A2 in colorectal cancer, so as to provide a basis for targeting those molecules in the clinical treatment of colorectal cancer." (PMID 35567291, 2022). "This study investigated the mechanisms of migration inhibitory factor (MIF) and solute carrier family 3 member 2 (SLC3A2) in colorectal cancer progression." (PMID 35567291, 2022). "In line with our findings, Cheon and co-workers recently demonstrated for other KRAS mutant colorectal cancer cells a bypass mechanism of refametinib resistance to MEK inhibition involving the activation of STAT3 and MAPK triggered by MIF overexpression." (PMID 31557914, 2019). "Our results provide the basis for a rational combination strategy against KRAS mutant colorectal cancers, predicated on the understanding of cross talk between the MEK and MIF pathways." (PMID 29896883, 2018). "In the first phase, 49 SNPs from six hypoxia pathway genes (HIF1A, HIF1B, HIF2A, LOX, MIF and CXCL12) in 272 colorectal cancer patients were analyzed." (PMID 25405996, 2014). "tRF-3022b, which may affect colorectal cancer tumor growth and polarization of M2 macrophages by binding LGALS1 and MIF." (PMID 40726981, 2025). "Finally, a nude mouse tumorigenicity assay was used to confirm the functions of MIF and SLC3A2 in colorectal cancer." (PMID 35567291, 2022). "In our study, we found that MIF (a soluble factor) could directly bind to SLC3A2 (a membrane‐binding factor) and regulate the function of colorectal cancer cells by promoting SLC3A2 expression." (PMID 35567291, 2022). "MIF and SLC3A2 might be potential biomarkers for monitoring the treatment of colorectal cancer." (PMID 35567291, 2022). "In addition, MIF has been suggested as a potential biomarker for hepatocellular carcinoma, colorectal cancer, gastric cancer and non-melanoma skin cancer." (PMID 26530123, 2015).
lung cancer (58 papers, 2007 to 2026). A malignant neoplasm involving the lung. "Polymorphisms in the promoter region of MIF, such as high-expression CATT repeats, influence MIF expression and susceptibility to a range of inflammatory, autoimmune, and malignant disorders, yet their role in lung cancer remains largely unexplored." (PMID 41898690, 2026). "In patients with lung cancer, MIF overexpression is associated with poor prognosis and is regarded as a candidate biomarker for non-small cell lung cancer." (PMID 41210694, 2025). "Nonetheless, elevated MIF levels have been consistently associated with increased proliferation and migration of lung cancer cells, reinforcing its potential as part of a diagnostic biomarker panel for lung cancer." (PMID 41159021, 2025). "Studies have reported that MIF is associated with an increased risk of multiple cancers, including breast, acute myeloid, colorectal, bladder, cervical, prostate, gastric and lung cancers." (PMID 37784249, 2023). "Overexpression of MIF has been reported in several cancer types, including lung cancer, and is associated with tumor progression, metastasis, and poor prognosis." (PMID 37359381, 2023). "Cisplatin resistant lung cancer cells showed an increased self-renewal ability and promoted M2 polarization of Tumor-associated microphages (TAMs) via the secretion of MIF." (PMID 32245422, 2020). "It discusses the significance of genetic predisposition, particularly high-expression MIF alleles, in guiding personalized treatment strategies for lung cancer and identifying patients who may derive benefit from MIF inhibition." (PMID 41898690, 2026). "Similarly, high MIF expression has been reported to be related to poor prognosis and a high risk of recurrence in lung cancer." (PMID 37784249, 2023). "Moreover, a previous study revealed that high MIF levels are associated with the risk of recurrence after lung cancer resection." (PMID 37784249, 2023). "Specifically, the lung cancer cells with resistance to cisplatin facilitates M2 polarization of tumor‐associated microphages (TAMs) through secreting MIF, thus accelerating angiogenesis and epithelial‐mesenchymal transition (EMT) as well as distant metastasis of lung cancer." (PMID 33314730, 2021). "We identified key metabolic pathways, including the novel finding of citric acid elevation and its interaction with the MIF gene, potential diagnostic biomarkers, as well as therapeutic targets, which may help guide future research and clinical management of lung cancer." (PMID 37359381, 2023). "This review discusses the dual role of MIF in inflammation and oncology, summarizes current therapeutic developments, and emphasizes the potential of MIF-targeted interventions in lung cancer." (PMID 41898690, 2026). "A MIF-directed proteolysis-targeting chimera (MIF-PROTAC) effectively degraded MIF and suppressed proliferation in lung cancer cells." (PMID 40835826, 2025). "Lung cancer cells release signals, including macrophage migration inhibitory factor (MIF), plasminogen activator inhibitor-1 (PAI-1), and IL-8, inducing astrocyte reactivity." (PMID 40345526, 2025). "It was found that their proliferation rate was still significantly lower than that of lung cancer cell lines after 48 hours of upregulation of MIF or HIF-1α, and the proliferation rate of MIF+AT2 was higher than that of DMOG and closer to tumor cells." (PMID 41210694, 2025). "During the lung cancer brain metastasis, lung cancer cells secrete IL-8, MIF, and PAI-1, which activate astrocytes and induce the expression of TNF-α, IL-1β, and IL-6, thereby promoting the proliferation of cancer cells." (PMID 41268299, 2025). "Lung cancer cell growth is aided by the MIF/NF-ƘB/HIF-1 pathway of macrophage migration inhibitory factor, which keeps the Warburg effect-related factors stable." (PMID 38919615, 2024).